EZH2 (enhancer of zeste 2 polycomb repressive complex 2 subunit)
Diseases named in the same sentence as EZH2 in open-access papers (continued):
Sharing a sentence is not in itself a finding about the gene and the disease.
atherosclerosis (25 papers, 2016 to 2025). A disease characterized by the build-up of fatty material and calcium deposition in the arterial wall resulting in partial or complete occlusion of the arterial lumen. "Multiple lines of evidence have implicated EZH2 up-regulation in the development and progression of atherosclerosis." (PMID 33988232, 2021). "We show that myeloid Ezh2 deficiency improves atherosclerosis outcome as lesion size was significantly reduced in Ezh2del transplanted mice compared to wildtype." (PMID 33574814, 2020). "We here show that myeloid Ezh2 deficiency also improves the outcome of atherosclerosis, another chronic inflammatory disease." (PMID 33574814, 2020). "We found that atherosclerosis was significantly reduced in Ezh2-deficient mice, correlating with impaired neutrophil migration and reduced foam cell inflammatory responses." (PMID 33574814, 2020). "In conclusion, we show that myeloid Ezh2 deficiency limits atherosclerosis due to impaired neutrophil migration and modulation of foam cell inflammatory responses." (PMID 33574814, 2020). "In Conclusion, myeloid Ezh2 deficiency impairs neutrophil migration and reduces macrophage foam cell inflammatory responses, both contributing to reduced atherosclerosis." (PMID 33574814, 2020). "In our in vivo study, EZH2 promoted the development of atherosclerosis in aortas of apoE−/− mice, which was associated with the higher DNA methylation level on ABCA1 promoter." (PMID 27295295, 2016). "A PCSK9 inhibitor was found to mitigate atherosclerosis by modulating the small nucleolar RNA host gene 16 (SNHG16)/enhancer of zeste homolog 2 (EZH2)/TNF receptor-associated factor 5 (TRAF5) axis, thereby restraining the migration, proliferation and formation of foam cells by VSMCs." (PMID 40354375, 2025). "In the context of atherosclerosis where EndMT is also associated with an upregulation of Snail, this indicates that the repression of EZH2 could reduce EndMT and therefore, contributes to the healthy endothelium." (PMID 33562658, 2021). "EZH2 plays an essential role in epigenetic maintenance and has been implicated in regulating multiple cellular processes during certain diseases, such as cancer and atherosclerosis." (PMID 27936205, 2016). "Many studies have shown that EZH2 plays a crucial role in cholesterol synthesis and atherosclerosis development." (PMID 37324939, 2023). "Studies have showed that EZH2 was demonstrated to be related to the occurrence and development of atherosclerosis." (PMID 35906216, 2022). "EZH2 overexpression leads to the development of atherosclerosis in ApoE−/− mice by catalyzing the methylation of DNMT1-mediated ATP binding cassette transporter A1, thereby inhibiting macrophage cholesterol efflux and promoting foam cell formation." (PMID 34568453, 2021). "EZH2 has been shown to promote foam cell formation by targeting ABCA1 thus accelerating atherosclerosis." (PMID 33988232, 2021). "Further evidence for a role for EZH2 in atherosclerosis is provided by its enhanced expression in atherosusceptible endothelium from disturbed blood flow regions of blood vessels." (PMID 33988232, 2021). "Overexpression of Ezh2 in all cell types was previously reported to promote macrophage foam cells formation and worsen atherosclerosis outcome." (PMID 33574814, 2020). "In line with their findings, we show that silencing of Ezh2 specifically in myeloid cells reduces atherosclerosis." (PMID 33574814, 2020). "To test this, we generated myeloid specific Ezh2 knockout mice and studied atherosclerosis progression." (PMID 33574814, 2020). "We here studied the role of the H3K27 methyltransferase EZH2 in atherosclerosis development by use of a myeloid-specific Ezh2 knockout mice." (PMID 33574814, 2020).
atherosclerosis (continued). "Because of its opposing function and importance of EZH2 in macrophage inflammatory responses, we here studied the role of myeloid EZH2 in atherosclerosis." (PMID 33574814, 2020). "Several EZH2 inhibitors are available and the use of these inhibitors in mouse models of atherosclerosis would be the next step to test the therapeutic potential of EZH2 inhibition to control atherosclerosis." (PMID 33574814, 2020). "Taken together, our data suggest that EZH2 is involved in the regulation of lipid accumulation and atherosclerosis development by inhibiting ABCA1-mediated cholesterol efflux." (PMID 27295295, 2016). "After above in vitro experiments, the effects of EZH2 on the atherosclerosis were examined in six-week-old male apoE−/− mice." (PMID 27295295, 2016). "Despite the promising outlook, further investigation is warranted to elucidate the epigenetic mechanisms mediated by EZH2 in VSMCs, which may pave the way for novel epigenetic therapies for conditions such as atherosclerosis and hypertension." (PMID 38994197, 2024). "suggesting that circEZH2 may regulate cholesterol synthesis and atherosclerosis development by regulating EZH2 expression." (PMID 37324939, 2023). "Notably, statins can reduce EZH2 expression levels in ECs, suggesting that they can serve as the potential therapeutic target in atherosclerosis treatment." (PMID 34568453, 2021). "Moreover, the endothelial cell-specific deletion of MAPK7 and EZH2 in atherosclerosis-prone mice would further emphasize their relevance to atherogenesis in future perspective." (PMID 34493753, 2021). "In addition, knockdown of GAS5 has the potential to prevent the progression of atherosclerosis by reducing enhancer of zeste homolog 2 (EZH2)-mediated ATP-binding cassette transporters A1 (ABCA1) transcription." (PMID 34781960, 2021). "The independent atherosclerosis risk factors dyslipidaemia, hyperhomocysteinemia, hyperglycaemia and OSS all block the expression of endothelial microRNAs that repress EZH2 translation under physiological conditions." (PMID 33562658, 2021). "Several studies have documented the involvement of EZH2 in atherosclerosis; however, the precise role of EZH2 in atherogenesis and the molecular mechanisms remain largely unknown." (PMID 27936205, 2016). "In this study, we investigated the effects of homocysteine (Hcy) on the expression of enhancer of zeste homolog 2 (EZH2), and tested our hypothesis that Hcy-induced atherosclerosis is mediated by increased EZH2 expression, which is regulated by miR-92a." (PMID 27936205, 2016). "We propose that EZH2 inhibitor could serve as therapeutic strategies for conditions like restenosis after angioplasty, atherosclerosis, and vein graft intimal thickening by inhibiting post-surgical VSMC proliferation and migration, thereby reducing restenosis incidence." (PMID 38994197, 2024). "Since the H3K27 methyltransferases have opposing effects on this histone mark and the fact that EZH2 controls macrophage inflammatory responses, we hypothesized that inhibition of the H3K27 methyltransferase EZH2 in myeloid cells improves atherosclerosis outcome." (PMID 33574814, 2020). "EZH2 also influences VSMC proliferation, migration, and vascular remodeling in conditions like atherosclerosis and abdominal aortic aneurysms." (PMID 39981435, 2025). "Our findings identified the direct interaction between enhancer of zeste homolog 2 (EZH2) and NEAT1 during atherosclerosis." (PMID 38646788, 2024). "GAS5 binds to EZH2 and then inhibits the expression of ABCA1, thus accelerating the progression of atherosclerosis." (PMID 34781960, 2021).
atherosclerosis (continued). "Ezh2 the methyltransferase corresponding to H3K27 promoted foam cell formation and the development of atherosclerosis in ApoE−/− mice." (PMID 32070413, 2020). "In support, recruitment of Dnmt1 by Ezh2 at the ABCA1 promoter is shown to transcriptionally silence ABCA1 expression, and accelerate progression of atherosclerosis." (PMID 29261844, 2017). "EZH2-induced downregulation of ABCA1 gene expression promotes foam cell formation and the development of atherosclerosis by DNA methylation of ABCA1 gene promoter." (PMID 27295295, 2016). "Conversely, EZH2 overexpression stimulated DNMT1-induced ABCA1 gene promoter methylation and atherosclerosis." (PMID 27295295, 2016). "EZH2 regulated miR-139-5p methylation and its target STAT1 expression through H3K27me3 and then promoted ox-LDL-induced HASMCs apoptosis, plaque formation, and inflammatory response in atherosclerosis mice." (PMID 37324939, 2023). "However, the role of miRNAs in EZH2 regulation in Hcy-induced atherosclerosis has not yet been fully elucidated." (PMID 27936205, 2016).
synovial sarcoma (25 papers, 2011 to 2025). "These epigenetic mechanisms in synovial sarcoma can be emphasized by an overexpression of EZH2 (enhancer of zeste homologue 2), which is described in poorly differentiated synovial sarcomas, and seems associated with a poorer prognosis." (PMID 34925348, 2021). "We observe that synovial sarcoma cell lines are sensitive to inhibition of EZH2, and that this sensitivity correlates with alteration of expression of certain genes previously implicated in synovial sarcoma." (PMID 27391784, 2016). "In summary, the fusion protein SS18-SSX in synovial sarcoma is believed to promote oncogenesis though either loss of negative regulation of EZH2/polycomb or by direct recruitment of EZH2/polycomb." (PMID 27125524, 2016). "A recent report suggests that a SS18-SSX fusion protein containing SWI/SNF complex in synovial sarcoma cell lines leads to displacement of PRC2/EZH2 at SOX2 loci, resulting in loss of the repressive H3K27Me3 marks and increased SOX2 expression." (PMID 27391784, 2016). "In our study, high expression of EZH2 was predominantly found in the poorly differentiated histological subtype of synovial sarcoma, which was associated with aggressive clinical behavior." (PMID 23110793, 2012). "Across all subtypes, EZH2 expression was found to correlate with the abundance of H3K27me3 motifs (ρ: 0.73, P<0.0001, R2=0.648), indicating causal relationship between EZH2 activity and the presence of the associated epigenetic marker in synovial sarcoma." (PMID 23110793, 2012). "In summary, EZH2 can be used as an auxiliary diagnostic and prognostic marker in the histopathologic evaluation of synovial sarcoma in addition to the markers currently in use." (PMID 23110793, 2012). "In synovial sarcoma the SS18-SSX may drive aberrant gene silencing through either loss of EZH2 inhibition or by direct recruitment to polycomb targets." (PMID 27125524, 2016). "Thus, SMARCB1-deficient synovial sarcoma represents an additional indication which may display clinical response to EZH2 inhibition." (PMID 27391784, 2016). "Here we show that preclinical models of synovial sarcoma—a cancer characterized by functional SMARCB1 loss via its displacement from the SWI/SNF complex through the pathognomonic SS18-SSX fusion protein—display sensitivity to pharmacologic inhibition of EZH2, the catalytic subunit of PRC2." (PMID 27391784, 2016). "The phase I study of tazemetostat, which targets the PRC2 catalytic subunit EZH2 (NCT02601937), included paediatric patients with relapsed or refractory RTs, other SMARCB1-deficient tumours, and synovial sarcoma." (PMID 40422882, 2025). "PRC2 performs chromatin silencing via its catalytic subunit Enhancer of Zeste 2 (EZH2), histone methyltransferase expressed in 76% of human synovial sarcoma samples." (PMID 39451213, 2024). "In epigenetic disorders with SSX-SS18 fusion gene origins, a candidate treatment target in synovial sarcoma shown by preclinical data is an enhancer of zeste homologue 2 (EZH2)." (PMID 30487384, 2018). "Further studies are needed to explore the relationship between SMARCB1 expression and EZH2 dependence in synovial sarcoma." (PMID 27391784, 2016). "This study demonstrates that synovial sarcoma is dependent on EZH2 for tumor survival and migration." (PMID 27125524, 2016). "Patients with stage II and stage III synovial sarcoma had significantly higher EZH2 scores (2.188 ± 0.3788, p = 0.0437 and 2.200 ± 0.3524, p = 0.0388, respectively) than stage I patients (1.077 ± 0.3483)." (PMID 27125524, 2016). "Taken together, dependence on EZH2 was observed in synovial sarcoma models in vitro, one xenograft model in vivo, as well as two of three PDX models in vivo." (PMID 27391784, 2016). "In summary, the data presented in this work suggest that synovial sarcomas, like MRTs, are SMARCB1-deficient tumors that are sensitive to EZH2 inhibition." (PMID 27391784, 2016).
synovial sarcoma (continued). "Given the importance of using model systems that most accurately recapitulate the clinical disease, we also investigated how synovial sarcoma PDX models respond to EZH2 inhibition in vivo." (PMID 27391784, 2016). "Knockdown of EZH2 by shRNA or siRNA resulted in inhibition of cell growth and migration across a series of synovial sarcoma cell lines." (PMID 27125524, 2016). "While this manuscript was under review an additional study using a structurally similar inhibitor of EZH2 also reported sensitivity to EZH2 inhibition in cell culture models of synovial sarcoma including additional cell line models." (PMID 27391784, 2016). "High expression of EZH2 helps to distinguish poorly differentiated synovial sarcoma from the monophasic and biphasic subtypes, and it is associated with unfavorable clinical outcome." (PMID 23110793, 2012). "Immunohistochemical stains of EZH2, H3K27me3, and Ki-67 were performed on tissue microarrays containing cores from 6 poorly differentiated, 39 monophasic and 10 biphasic synovial sarcomas, and evaluated by pre-established scoring criteria." (PMID 23110793, 2012). "Although the target genes of EZH2-mediated silencing in synovial sarcoma still wait to be identified, EZH2 activity is generally thought to favor the conservation of undifferentiated state and give way to rapid proliferation." (PMID 23110793, 2012). "EZH2 overexpression in synovial sarcoma is correlated with high H3K27 trimethylation, indicating a functional participation of EZH2 in PRC2." (PMID 23110793, 2012). "Our findings indicate that the link between EZH2 expression, high mitotic activity, and undifferentiated morphology exists in synovial sarcoma as well, since EZH2 scores strongly correlated with those of Ki-67 and were highest in poorly differentiated tumors." (PMID 23110793, 2012). "Specifically, SYT-SSX2 represses the expression of the tumor suppressor gene early growth response 1 (EGR1), a regulator of cell cycle, engaging EZH2 on the EGR1 promoter in synovial sarcoma cells." (PMID 21609503, 2011). "While cell line-based xenograft studies yielded further evidence for the anti-synovial sarcoma activity of EZH2 inhibitor, inconsistencies in drug efficacy were seen among the mouse models implanted with primary tumor tissues from different synovial sarcoma patients." (PMID 40296913, 2025). "In addition, poorly differentiated synovial sarcoma showed high expression of EZH2, which was predictive for distant metastasis." (PMID 29415665, 2018). "Some studies exist on synovial sarcoma revealed that EZH2 expressed in 76% of patients." (PMID 30120321, 2018). "In synovial sarcoma, where SS18-SSX is aberrantly expressed, it is hypothesized that EZH2 overactivity, either from loss of SWI/SNF-mediated EZH2 inhibition or by direct recruitment of EZH2 to polycomb targets, leads to tumorigenesis." (PMID 27125524, 2016). "We additionally observed sensitivity to EZH2 inhibition in a SMARCB1-deficient synovial sarcoma xenograft, but not a synovial sarcoma xenograft expressing wild-type levels of SMARCB1." (PMID 27391784, 2016). "We subsequently investigated EZH2 as a therapeutic target in synovial sarcoma in vitro." (PMID 27125524, 2016). "Given the sensitivity of SMARCB1-deficient tumors to EZH2 inhibition, and the diminution of SMARCB1 levels observed in SS18-SSX translocation positive synovial sarcomas, we hypothesized that synovial sarcomas may be similarly dependent on PRC2/EZH2 activity." (PMID 27391784, 2016). "Indeed, we find that in vitro, SS18-SSX translocation-positive synovial sarcoma cell lines are sensitive to the EZH2 inhibitor tazemetostat." (PMID 27391784, 2016). "We first confirmed the presence of EZH2 in human synovial sarcoma samples." (PMID 27125524, 2016). "Additionally, the effects of doxorubicin as a monotherapy or in combination with EZH2 inhibition were examined as doxorubicin is a standard of care for the treatment of patients with synovial sarcoma." (PMID 27391784, 2016).